RUNDC3B (RUN domain containing 3B)
Synonyms: RPIB9; RPIP9
Tractability: PROTAC: its protein half-life has been measured.
Safety:
Unwanted effects reported when the protein is acted on. In parentheses: how it was acted on, where the effect was seen, and who reports it.
hypercholesteremia (source: ClinPGx)
Gene: Protein-coding gene on chromosome 7 (87,627,548 to 87,832,296, forward strand). Ensembl gene ENSG00000105784.
Subcellular location (Human Protein Atlas): Intermediate filaments; Basal body; Centrosome; Cytokinetic bridge; Cytosol; Primary cilium
Genetic constraint (gnomAD): Loss-of-function variants: 11 observed, 26.13 expected, observed/expected ratio (o/e) 0.42, 90% interval 0.26 to 0.7. The upper end of that interval is the gene's LOEUF score, 0.7, which puts it in group 2 of 6, group 1 being the genes least tolerant of losing a copy. Missense variants: 226 observed, 243.78 expected, observed/expected ratio (o/e) 0.93, 90% interval 0.83 to 1.03. Synonymous variants: 89 observed, 90.61 expected, observed/expected ratio (o/e) 0.98, 90% interval 0.83 to 1.17.
Homologues: Orthologues: chimpanzee RUNDC3B (100% identical), macaque RUNDC3B (99% identical), dog RUNDC3B (98% identical), mouse Rundc3b (95% identical), pig RUNDC3B (94% identical), rat Rundc3b (94% identical), tropical clawed frog rundc3b (81% identical), guinea pig RUNDC3B (79% identical), zebrafish rundc3b (73% identical), Drosophila melanogaster CG31064 (19% identical), Drosophila melanogaster CG6051 (10% identical), Caenorhabditis elegans lst-2 (9% identical). Paralogues in human: RUNDC3A (54% identical), RUFY3 (25% identical), RUFY1 (24% identical), RUFY2 (23% identical), SNX29 (21% identical), ZFYVE26 (19% identical), PLEKHM2 (17% identical), ZFYVE28 (11% identical), ZFYVE1 (10% identical), ZFYVE19 (10% identical), ZFYVE16 (7% identical), PLEKHF1 (7% identical), and 1 more.
Diseases named in the same sentence as RUNDC3B in open-access papers:
RUNDC3B is named in the same sentence as 13 diseases in open-access papers, as found by Europe PMC text mining. Sharing a sentence is not in itself a finding about the gene and the disease. The quoted sentences say what the papers report.
breast carcinoma (4 papers, 2012 to 2023). "RUNDC3B is likely involved in multiple Ras-like GTPase signaling pathways and is implicated in transformation and progression of breast cancer." (PMID 25057852, 2014). "RUNDC3B has been related to a more metastatic phenotype in breast cancer patients." (PMID 22846052, 2012).
Stillbirth (2 papers, 2020 to 2023). Death of the fetus in utero after at least 22 weeks of gestation. "RUN Domain Containing 3B (RUNDC3B) on chromosome 4 had been reported to the retained placenta signals with associations related to milk production, productive life, and health and reproduction traits, including calving ease and stillbirth." (PMID 38002947, 2023).
teratozoospermia (2 papers, 2021 to 2022). "Ultimately, we screened to obtain three potential biomarker genes with the highest differential expression in the teratozoospermia group of patients, AGBL4, FAM172A and RUNDC3B." (PMID 33819193, 2021).
endometrioid tumor (1 paper, 2019). A benign, borderline, or malignant epithelial tumor of the female reproductive system characterized by the presence of glands and/or cysts lined by neoplastic cells that resemble endometrial cells. "ANO1, SOX17, CGNL1, DACH1, RUNDC3B, SH3YL1 and CRISPLD1 were significantly downregulated both in papillary serous tumors and endometrioid tumor." (PMID 30813939, 2019).
meningioma (1 paper, 2018). A generally slow growing tumor attached to the dura mater. "RUNDC3B, SCG2, SLC1A3, EXT1 (as well as RHOBTB3, TSPAN7, CAV2, MLPH) were part of the NF2/SMARCB1 expression subclass of a recent study on genomic profiling of meningioma." (PMID 29662628, 2018). "Six of these genes were usually underexpressed (RUNDC3B, ANGPT2, PHLDA2, CAV2, EDNRA, and SCG2) in non-aggressive/non-recurrent tumors and overexpressed in more aggressive/recurrent meningiomas." (PMID 29662628, 2018).
pancreatic carcinoma (1 paper, 2012). "According to this, we could speculate a selection of RUNDC3B expression in colon and pancreatic carcinoma cell lines, instead of a functional Pgp protein expression, since expression of RUNDC3B could represent an additional advantage in their evolution to a more aggressive phenotype." (PMID 22846052, 2012).
prostate hyperplasia (1 paper, 2024). "To delve deeper into the potential mechanisms of DACH1, CACNA1D, STARD13, and RUNDC3B in regulating prostate hyperplasia, we stratified prostate hyperplasia samples according to the levels of expression of these genes and conducted GSEA." (PMID 39703506, 2024). "ROC curves were then used to assess the predictive potential of these key gene markers in prostate enlargement, revealing AUC values of 0.885, 0.874, 0.885, and 0.874 for DACH1, CACNA1D, STARD13 and RUNDC3B, respectively." (PMID 39703506, 2024).
cancer (4 papers, 2014 to 2024). A tumor composed of atypical neoplastic, often pleomorphic cells that invade other tissues. "Gain and amplification of 7q22.11q31.1 are associated with an increased expression of several genes postulated to be implicated in cancer, including RUNDC3B, PPP1R9A and ABCB1, a known multidrug resistance gene." (PMID 25057852, 2014). "The correlation heatmap showed that PDE2A was positively associated with SEMA6B, RUNDC3B, MICU3, and KCNK3 genes in the majority of cancers." (PMID 39699377, 2024). "High-risk prognostic genes BMP4, CELSR3, GPRC5C, and RUNDC3B, highly expressed in Epithelial Cells, CCBE1 showed expression in Leydig cells, SCGB2A2 highly expressed in Epithelial Cells and Cancer cells, suggesting that Epithelial cell play an important role in tumor growth and initiation." (PMID 37985782, 2023). "The identification of SEMA6B, RUNDC3B, MICU3, and KCNK3 as top PDE2A-correlated genes provided novel targets for functional validation studies aimed at elucidating the molecular mechanisms underlying PDE2A's role in cancer." (PMID 39699377, 2024).
RUNDC3B also shares sentences with these, for which no sentence is quoted: acute myelogenous leukemia (1 paper); Azoospermia (1); Barrett’s oesophagus (1); epilepsy (1); tumor (1).